CST2 (cystatin SA)
Description:
Thiol protease inhibitor.
Tractability: Antibody: UniProt places it where antibodies can reach, with high confidence; UniProt predicts a signal peptide or a membrane-spanning region; its Gene Ontology location is reachable by antibodies, with medium confidence.
Gene: Protein-coding gene on chromosome 20 (23,823,769 to 23,826,729, reverse strand). Ensembl gene ENSG00000170369.
Subcellular location: Secreted
Gene Ontology:
Molecular function: protein binding; cysteine-type endopeptidase inhibitor activity
Biological process: detection of chemical stimulus involved in sensory perception of bitter taste
Cellular component: extracellular region; cytoplasm; vesicle
Genetic constraint (gnomAD): Loss-of-function variants: 30 observed, 17.94 expected, observed/expected ratio (o/e) 1.67, 90% interval 1.23 to 1.95. The synonymous counts are far from expectation, so gnomAD's model fits this gene poorly and the ratio says little. Missense variants: 243 observed, 175.1 expected, observed/expected ratio (o/e) 1.39, 90% interval 1.25 to 1.54. Synonymous variants: 105 observed, 74.06 expected, observed/expected ratio (o/e) 1.42, 90% interval 1.21 to 1.67.
Homologues: Orthologues: chimpanzee CST1 (93% identical), macaque CST2 (84% identical), zebrafish si:busm1-57f23.1 (23% identical), Caenorhabditis elegans cpi-1 (19% identical), Caenorhabditis elegans cpi-2 (17% identical), Caenorhabditis elegans K08B4.7 (7% identical). Paralogues in human: CST4 (88% identical), CST1 (86% identical), CST3 (59% identical), CST5 (56% identical), CST6 (30% identical), CST8 (27% identical), CST7 (26% identical), CSTL1 (26% identical), CST9L (26% identical), CST11 (24% identical), CST9 (21% identical).
Diseases named in the same sentence as CST2 in open-access papers:
CST2 is named in the same sentence as 41 diseases in open-access papers, as found by Europe PMC text mining. Sharing a sentence is not in itself a finding about the gene and the disease. The quoted sentences say what the papers report.
cyst (9 papers, 2019 to 2025). A sac-like closed membranous structure that may be empty or contain fluid or amorphous material. "Nonetheless, it is indubitable that CST2 is an antigen highly sought after as knocking out these genes completely inhibited cyst formation in the brains of mice." (PMID 37104285, 2023). "This study revealed 5 new bradyzoite-upregulated GRAs which localized to the tissue cyst wall and cyst matrix (named CST2 –CST6)." (PMID 32374791, 2020). "This analysis yielded an inventory of previously undescribed cyst wall proteins (CST2/GRA50, CST3/GRA51, CST4, CST5/GRA52, and CST6/GRA53) that were validated to localize to the cyst wall by immunofluorescence." (PMID 32019789, 2020). "To expand on the functions of these proteins at the cyst wall, we knocked out two of these proteins, CST2 and CST3, using a recyclable selectable marker strategy and characterized these transgenic parasites for their ability to form cysts." (PMID 31040239, 2019). "This may reflect an inability to establish chronic infection in vivo, and it is possible that the reduced cyst burden observed in infection with CST2-KO parasites may be partially due to reduced dissemination of the parasite to the central nervous system during acute infection." (PMID 31040239, 2019). "Since only CST2-BirA*, CST4-BirA*, CST9-BirA*, and MCP3-BirA* parasites showed biotin ligase activity at the cyst wall, streptavidin affinity capture of the potential interacting partners of these cyst wall strains was performed and processed by LC-MS/MS." (PMID 32019789, 2020). "The ultrastructure of in vitro CST2-HA, KO, and COMP cysts were examined by electron microscopy to further assess the role of CST2 in cyst morphology." (PMID 31040239, 2019). "In addition, bradyzoite-specific GRAs, including GRA55 and GRA59, are essential for cyst formation, with the deletion of certain GRAs, such as CST2 and GRA55, leading to a significant reduction in cyst burden in vivo." (PMID 40941387, 2025). "Two other cyst wall proteins, CST2 and CST3, were also studied and their respective knock out strains revealed a normal phenotype with respect to growth or cyst formation in vitro, yet, CST2-KO parasites were markedly less virulent during the acute infection in mice." (PMID 34262559, 2021). "Of these, CST2/GRA50 was important for parasite virulence and establishment of cyst burden." (PMID 32374791, 2020). "While the deletion strains do not display an abnormal phenotype with respect to growth or cyst formation in vitro, CST2-KO parasites are markedly less virulent during acute infection in mice." (PMID 31040239, 2019). "CST2-KO parasites were highly attenuated in virulence and did not establish detectable cyst burdens." (PMID 31040239, 2019). "Furthermore, these GRAs are expressed in bradyzoites and co-localize with both GRA12 and DBA, suggesting that they may contribute to cyst formation and maintenance, similar to other well-known cyst-related GRAs such as GRA12, GRA76, and CST2." (PMID 40941387, 2025). "CST2 knockouts show an attenuated virulence, and no cyst is detected in mice." (PMID 37426671, 2023). "Given that no cysts were detected after the mice were infected with CST2-KO parasites, we hypothesized that CST2 might be involved in the formation of a functional cyst wall." (PMID 31040239, 2019). "The absence of CST2 within other BirA* pulldowns may be due to a detection limit of CST2 if this protein is not very abundant within the cyst wall or if CST2 only interacts with the N termini of these other bait proteins, which may be too far from the C-terminally located BirA* tag." (PMID 32019789, 2020). "When no exogenous biotin was provided, CST2-BirA*, CST4-BirA*, CST9-BirA*, and MCP3-BirA* strains showed no increase in streptavidin signal at the cyst wall." (PMID 32019789, 2020).
gastric cancer (7 papers, 2021 to 2025). A primary or metastatic malignant neoplasm involving the stomach. "CST2 encodes a thiol protease inhibitor which was found to be associated with tumorigenesis as well as poor prognosis in breast and gastric cancers." (PMID 36439479, 2022). "In recent years, mounting evidence has shown the overexpression of CST2 in gastric cancer, colorectal cancer, prostate cancer, hepatocellular carcinoma, and breast cancer." (PMID 39926600, 2024). "One study employed bioinformatics to identify CST2 as a potential prognostic marker in gastric cancer." (PMID 38717526, 2024). "In gastric cancer, CST2 promotes tumor cell growth, migration, and invasion by modulating EMT and the TGF-β1 signaling pathway." (PMID 39926600, 2024). "To investigate the involvement of the PI3K/AKT signaling pathway in the oncogenic mechanism of CST2 in gastric cancer, we assessed the relationship between CST2 and p-PI3K, p-AKT, and other apoptosis-related proteins." (PMID 38717526, 2024). "This study confirms that CST2 expression in gastric cancer tissues and cell lines is significantly lower than in normal gastric tissues and epithelial cells." (PMID 38717526, 2024). "CST2 was screened out to be further explored its effects on gastric cancer, according to our preliminary experiments." (PMID 38717526, 2024). "Compared to the negative control (NC) groups, phosphorylation levels of PI3K and AKT were significantly reduced following CST2 overexpression, indicating CST2’s inhibition of PI3K/AKT pathway activation in gastric cancer." (PMID 38717526, 2024). "In gastric cancer samples, CST2 is upregulated, enhancing tumor cell growth, migration, and invasion by regulating epithelial-mesenchymal transition (EMT) and the TGF-β1 signaling pathway, leading to poor prognosis in patients." (PMID 39926600, 2024). "This positions CST2 as a potential prognostic marker and therapeutic target for treating gastric cancer." (PMID 38717526, 2024). "The results suggest that AKT activation can counteract the inhibitory effects of CST2 overexpression on gastric cancer cells, implying that CST2 exerts its effects through the AKT pathway." (PMID 38717526, 2024). "The results demonstrated a significant enhancement of oxaliplatin sensitivity in gastric cancer cells overexpressing CST2." (PMID 38717526, 2024). "While potential molecular mechanisms and related signaling pathways of CST2 have been identified, it is important to note that these findings are primarily based on gastric cancer." (PMID 39926600, 2024). "We determined and confirmed that CST2 can suppress the malignant biological behaviors of gastric cancer cells, including cellular proliferation, migration, and invasion." (PMID 38717526, 2024). "We observed that the effects by CST2 on gastric cancer cells may be mediated by inhibition of PI3K/AKT pathway." (PMID 38717526, 2024). "Finally, in gastric cancer cell lines, we will investigate the impact of CST2 knockout on expression levels, clonal proliferation, cell apoptosis, and cell migration." (PMID 39926600, 2024). "In addition, multiple assays, including cell proliferation, colony formation, wound-healing, and transwell migration/invasion, were considered to ascertain the influence of CST2 overexpression on gastric cancer." (PMID 38717526, 2024). "Furthermore, we performed molecular biology validation in gastric cancer to further confirm the oncogenic role of CST2." (PMID 39926600, 2024). "Furthermore, CST2 was demonstrated to improve chemosensitivity to Oxaliplatin in gastric cancer cells through the PI3K/AKT signaling pathway." (PMID 38717526, 2024). "Additionally, CST2 enhances the chemosensitivity of gastric cancer cells to the oxaliplatin, an effect observed specifically in gastric cancer cells without affecting normal gastric epithelial cells." (PMID 38717526, 2024). "This study aims to explore the expression and function of CST2 in gastric cancer." (PMID 38717526, 2024).
gastric cancer (continued). "In conclusion, our findings suggest that CST2 may modulate both the activity and the drug resistance of gastric cancer cells by inhibiting the PI3K/AKT signaling pathway." (PMID 38717526, 2024). "High CST2 expression led to a poor prognosis in gastric cancer patients." (PMID 34676211, 2021). "Accordingly, in this study, we investigate CST2’s role in GC carcinogenesis and subsequently validated CST2’s functions using normal gastric cells, gastric cancer cells, and samples from GC patients." (PMID 38717526, 2024). "We ascertained that CST2 possesses the ability to suppress the malignant biological behaviors of gastric cancer cells, including cellular proliferation, migration, and invasion, and to enhance the chemosensitivity of gastric cancer cells to the chemotherapeutic agent oxaliplatin." (PMID 38717526, 2024). "CST2 may serve as a tumor suppressor gene increasing sensitivity to Oxaliplatin in gastric cancer." (PMID 38717526, 2024). "CST2 expression at the protein level was decreased to be reduced in both gastric cancer tissues and cell lines, and CST2 expression attenuate gastric cancer growth, an effect restricted to gastric cancer cells and absent in gastric epithelial GES-1 cells." (PMID 38717526, 2024). "Additionally, CST2 was found to attenuate the growth of gastric cancer cells and to enhance sensitivity to Oxaliplatin through the PI3K/AKT signaling pathway, specific to gastric cancer cell lines." (PMID 38717526, 2024).
breast carcinoma (6 papers, 2019 to 2025). "In breast cancer, increased expression of the CST2 gene has been shown to be associated with tumor cell proliferation, movement, and adhesion." (PMID 36768739, 2023). "The upregulation of CST2 has been linked to breast cancer development." (PMID 39926600, 2024). "Oncogenic expression of CST2 has been documented to promote bone metastasis in breast cancer, borne out by its upregulated stage-III salience here." (PMID 41048341, 2025). "Previous studies showed that CST2 was expressed higher in breast cancer tissues compared with normal mammary tissues." (PMID 34676211, 2021). "More study should be performed to confirm the function and character of CST2 in the development of breast cancer." (PMID 31182966, 2019). "Finally, 6 upregulated DEGs (CST2, DRP2, CLEC5A, SCD, KIAA1211, DTL) and 6 downregulated DEGs (STAC2, BTNL9, CA4, CD300LG, GPIHBP1 and PIGR), were confirmed in a quantitative real time PCR comparison of breast cancer and paracancerous breast tissues from 8 clinical specimens." (PMID 31182966, 2019).
bladder cancers (3 papers, 2021 to 2025). "Moreover, a global secretome analysis has demonstrated that elevated expression of CST2 could promote bone metastasis in breast and bladder cancers." (PMID 34696780, 2021). "In bladder cancer tissues, CST1, CST2, CST6, CSTA, and CSTB were significantly upregulated, while CST3 and CST7 were downregulated compared to benign tissues." (PMID 40747123, 2025). "Our results revealed that CST1/CST2/CST6 genes were significantly upregulated, whereas CST3/CTS7 genes were downregulated in bladder cancers." (PMID 40747123, 2025).
prostate carcinoma (3 papers, 2023 to 2025). A carcinoma that arises from epithelial cells of the prostate gland. "Previous studies by Xiaohan Ren, Anqi Cheng, and others also identified CST2 as a risk factor for prostate cancer." (PMID 37346077, 2023). "Additionally, CST2 may be involved in prostate cancer cell migration through the regulation of the EMT signaling pathway." (PMID 39926600, 2024). "CST2 may participate in prostate cancer metastasis by modulating the EMT signaling pathway." (PMID 39926600, 2024).
chronic rhinosinusitis (2 papers, 2021 to 2024). Chronic form of sinusitis. "Previous studies have revealed that CST2 might play a positive role in predicting the course of some diseases, such as allergic rhinitis 39, chronic rhinosinusitis with nasal polyps 40, and periodontal disease." (PMID 34335931, 2021).
colorectal cancer (2 papers, 2021 to 2024). A primary or metastatic malignant neoplasm that affects the colon or rectum. "Elevated levels of CST2 in colorectal cancer are associated with shortened overall survival in patients." (PMID 39926600, 2024).
ovarian carcinoma (2 papers, 2019 to 2025). A malignant neoplasm originating from the surface ovarian epithelium. "Till now, few studies have focused on CST2 in any tumor type, except to show that is responsive to the anti-growth activity of triptolide in ovarian cancer cells." (PMID 31182966, 2019).
stomach adenocarcinoma (2 papers, 2021 to 2024). "In summary, CST2 is upregulated in various tumor types and is associated with unfavorable prognosis in stomach adenocarcinoma." (PMID 39926600, 2024). "In stomach adenocarcinoma (STAD), CST2-related risk models are associated with prognosis and demonstrate strong predictive capabilities, while also being closely linked to the immune microenvironment." (PMID 39926600, 2024).
bladder tumor (1 paper, 2025). "The pronounced upregulation of the cystatin family members CST2 and CST4 suggests altered protease–antiprotease balance during bladder tumor progression." (PMID 41154349, 2025).
breast tumors (1 paper, 2019). "Just like the CST2, GJB2, UBE2T, NUF2 and ORC6 also showed the same high expression level in breast tumors." (PMID 31182966, 2019).
colorectal adenoma (1 paper, 2021). An adenoma that arises from the colon or rectum. "Consistently, database analysis and IHC-based TMA analysis confirmed that colorectal adenoma and carcinoma tissues had clearly higher CST2 expression at both the mRNA and/or protein level compared to normal colorectal tissues or matched noncancerous adjacent tissues." (PMID 34335931, 2021). "TMA also revealed that colorectal adenoma, CRC, and metastatic CRC tissues exhibited a significantly increased CST2 protein expression." (PMID 34335931, 2021). "In conclusion, the present study revealed that colorectal adenoma and carcinoma tissues had significantly higher CST2 expression compared to noncancerous colorectal tissues at both the mRNA and protein levels." (PMID 34335931, 2021).
eosinophilia (1 paper, 2023). "The results of the biomarker analysis showed that periostin, PAPP-A, CST-2, SerpinF2 and eosinophilia showed similar courses to NPS." (PMID 36969262, 2023).
hepatocellular carcinoma (1 paper, 2024). A malignant tumor that arises from hepatocytes. "CST2 is associated with overall survival rate (OS) in hepatocellular carcinoma." (PMID 39926600, 2024).
keratoconus (1 paper, 2026). A degenerative, structural disorder of the eye, characterized by a cone-shaped protrusion of the cornea. "Cystatins (CST2, CST3, CST5), key inhibitors of cysteine proteases, were also decreased, potentially contributing to increased proteolytic activity and stromal degradation—an established pathogenic mechanism in keratoconus." (PMID 41601845, 2026).
lung disease (1 paper, 2024). "The cysteine protease inhibitors cystatin B, cystatin SA and lipocalin-1 are decreased in frequent exacerbators, but their specific role in lung disease has not been characterised." (PMID 38135443, 2024).
pancreatic cancer (1 paper, 2024). "A recent study discovered that CST2 is overexpressed in pancreatic cancer, functioning as an oncogene." (PMID 39926600, 2024). "Previous studies have demonstrated that overexpression of CST2 contributes to the progression of pancreatic cancer." (PMID 39926600, 2024). "Knockdown of CST2 in pancreatic cancer inhibits tumor cell proliferation, migration, and invasion, while also suppressing the activation of the PI3K/AKT signaling pathway." (PMID 39926600, 2024). "Recently, a study has suggested that CST2 may promote the malignant progression of pancreatic cancer through the activation of the PI3K AKT signaling pathway." (PMID 39926600, 2024).
periodontitis (1 paper, 2022). An acute or chronic inflammatory process that affects the tissues that surround and support the teeth. "Recently, proteomic analysis of the saliva of Grade B Stage 2 periodontitis patients revealed that histatin-1, proline-rich phosphoprotein, thioredoxin, and cystatin-SA were increased in Grade B Stage 2 periodontitis." (PMID 35330371, 2022).
Uterine corpus endometrioid carcinoma (1 paper, 2024). "The predominant mutation type observed is “Mutation,” with the highest mutation frequency of CST2 found in Uterine corpus endometrioid carcinoma." (PMID 39926600, 2024).